FGFR1 (fibroblast growth factor receptor 1)
Diseases named in the same sentence as FGFR1 in open-access papers (continued):
Sharing a sentence is not in itself a finding about the gene and the disease.
hyperphosphatemia (17 papers, 2013 to 2025). Abnormally high level of phosphate in the blood. "Hyperphosphataemia associated with FGFR inhibition appears to be mediated by FGF23 signalling through FGFR1." (PMID 28972963, 2017). "In addition, tissue specific modulation of FGFR1 can conceivably counteract conditions associated with FGF23 resistance or chronic hyperphosphatemia, such as those seen in patients with chronic kidney disease." (PMID 23451204, 2013). "On-target hyperphosphatemia, attributable to the role of FGFR1 in phosphate homeostasis, limits optimal dosing of FGFR1-3 inhibitors." (PMID 40014401, 2025). "Relatedly, growth of renal cell carcinoma is claimed to depend on dysregulation of the FGF/FGF-receptor 1 (FGFR1) cell signaling pathway, yet pharmaceutical inhibition of this pathway blocks circulating levels of FGF23 and causes hyperphosphatemia." (PMID 40643473, 2025). "Hyperphosphatemia is a very common adverse effect of FGFR inhibitors because the FGFR1 signaling pathway is a fundamental mechanism to limit the phosphate reabsorption in the proximal renal tubule by inhibiting the phosphate co-transporters." (PMID 38255923, 2024). "Hyperphosphatemia, a direct on-target toxicity due to FGFR1 in renal tubule, was observed in a dose-dependent and exposure-dependent fashion." (PMID 38602417, 2024). "The patient experienced low-grade hypercalcaemia and hyperphosphataemia: these derive from inhibition of FGFR1 (most compounds in late clinical development have pan-FGFR-inhibitory activity; FGFR2-selective agents are in early drug development)." (PMID 38895132, 2024). "Reductions of FGFR1 expression in the proximal tubule resulted in hyperphosphatemia and resistance to the phosphaturic effects of administered recombinant FGF-23." (PMID 26839958, 2016). "Second, soluble Klotho remedies hyperphosphatemia through interaction with FGFR1 in the kidney." (PMID 36338347, 2022). "Most of the FGFR1 inhibitors lack good kinase selectivity, its efficiency can be affected when high intracellular concentration of ATP exists, and they also result in a variety of side effects like nausea, weakness, hyperphosphataemia, and elevated blood pressure during clinical trial." (PMID 24980830, 2014). "In patients with advanced solid tumours treated with the FGFR1,2,3 inhibitor AZD3547, the common treatment-related AEs included fatigue, mucositis, nausea, CSR, and hyperphosphataemia." (PMID 28972963, 2017). "The dose-limiting toxicities due to inhibition of FGFR1/FGFR3 and FGFR4 are hyperphosphatemia and the blockade of bile acid synthesis, respectively." (PMID 27029060, 2016). "By inhibiting FGFR1, Erdafitinib reduces FGF23 levels, which diminishes the inhibition of sodium-phosphate co-transporters in renal proximal tubules, thereby increasing renal phosphate reabsorption and resulting in hyperphosphatemia." (PMID 39712492, 2024). "Fgfr1PT-cKO mice exhibited an increase in sodium-dependent phosphate co-transporter expression, hyperphosphatemia, and refractoriness to the phosphaturic actions of FGF-23, consistent with a direct role of FGFR1 in mediating the proximal tubular phosphate responses to FGF-23." (PMID 26839958, 2016).
urothelial carcinoma (17 papers, 2012 to 2025). A malignant neoplasm derived from the transitional epithelium of the urinary tract (urinary bladder, ureter, urethra, or renal pelvis). "Current evidence indicates that Erdafitinib exhibits certain therapeutic efficacy in the treatment of advanced solid tumors harboring FGFR1–4 mutations, with the most pronounced therapeutic effect observed in urothelial carcinoma." (PMID 40860823, 2025). "Next-generation sequencing was prospectively performed on urinary tract carcinomas for the detection of FGFR1-4 alterations at 2 tertiary care centers (2021-2025), using the Oncomine Comprehensive Assay (OCA) v3 DNA and OCA Plus RNA." (PMID 41097827, 2025). "The detection rate for FGFR1-4 alterations in a real-world, dual-institution cohort of urinary tract carcinomas was reported." (PMID 41097827, 2025). "In a Phase II study, erdafitinib, a tyrosine kinase inhibitor of FGFR1–4, exhibits antitumor activity in advanced urothelial carcinoma with FGFR alterations." (PMID 35864158, 2022). "Recently, the FORT-1 phase II/III trial, led by Sternberg and colleagues, demonstrated that rogaratinib and chemotherapy had comparable efficacy and safety in patients with metastatic/advanced urothelial carcinoma exhibiting FGFR1/3 messenger RNA overexpression." (PMID 41097827, 2025). "Similarly, the FGFR1 and FGFR3 dual inhibitor PD173074 blocked cell cycle progression and caused apoptosis in lung, head and neck, breast, and urothelial carcinoma cells." (PMID 34639155, 2021). "The FGFR1 inhibitor SU5402 was shown to reduce the survival of breast, lung, and urothelial carcinoma cells." (PMID 34639155, 2021).
esophageal cancer (16 papers, 2010 to 2023). A primary or metastatic malignant neoplasm involving the esophagus. "In summary, the results of our study provide strong evidence that FGFR1 amplification is an early molecular event linked to the squamous cell subtype of esophageal cancers." (PMID 26555375, 2015). "Partial response was confirmed in one patient with FGFR1-mutant esophageal carcinoma and one with FGFR2-mutant cholagiocarcinoma." (PMID 37889382, 2023). "Little is known about the clinical significance of FGFR1 amplification in esophageal cancer or about possible differences between histological subtypes." (PMID 26555375, 2015). "Data from The Cancer Genome Atlas (TCGA) on 70 esophageal carcinomas (45 ESCC and 25 EADC) suggest that FGFR1 mutations are rare events (< 2%) in this tumor type." (PMID 26555375, 2015). "In previous studies, it has been shown that the genes and proteins of FGFR-1 and MMP3 are highly expressed in esophageal squamous cell carcinoma, and may be associated with esophageal cancer invasion and metastasis." (PMID 35227278, 2022). "In addition, the FGF2-mediated FGFR1 signaling pathway regulates the survival and migration of TAMs in the tumor microenvironment in esophageal cancer." (PMID 30811474, 2019). "Furthermore, FGF2 secreted from esophageal cancer cells promotes macrophage migration and survival through FGFR1 signaling." (PMID 31681612, 2019). "The high homogeneity of FGFR1 amplification suggests that patients with FGFR1 amplified esophageal cancers may particularly benefit from anti-FGFR1 therapies and prompt for clinical studies in this tumor type." (PMID 26555375, 2015). "The lack of relevant intratumoral heterogeneity of FGFR1 amplifications in our study suggests that anti-FGFR1 therapies may be effective in esophageal cancers harboring this alteration, and encourages future clinical trials in FGFR1 amplified ESCC." (PMID 26555375, 2015). "For example, in the tumor microenvironment of esophageal cancer, NCAM- and FGF-2-mediated FGFR1 signaling modulates the survival and migration of tumor-associated macrophages and cancer cells." (PMID 36303551, 2022).
myeloid neoplasm (16 papers, 2012 to 2024). Proliferation of myeloid cells originating from a primitive stem cell. "Futibatinib, an oral selective small molecule inhibitor of FGFR1-4, given at an oral dose of 20 mg once daily, has been assessed in a 55-year-old male, resulting in the first reported case of complete hematologic and cytogenetic remission in an FGFR1-driven myeloid neoplasm." (PMID 39037514, 2024). "Of the two tumors with dual FGFR1 + PIK3R1 mutations, one contained an accompanying PTPN11 mutation (p.A72T), which is a known mutational hotspot in myeloid neoplasms thus providing support for pathogenicity [Catalog of Somatic Mutations in Cancer database v91 release]." (PMID 32859279, 2020). "Other neoplastic myeloid conditions have been associated with monocytic abnormalities including juvenile myelomonocytic leukemia, chronic myeloid leukemia with p190 fusion, and myeloid neoplasm with rearrangements of PDGFRA, PDGFRB, FGFR1 and PCM1-JAK2." (PMID 34073699, 2021). "It is worth noting that a diagnosis of MPN-U cannot be made in cases with genetic lesions defining other myeloid neoplasms (BCR-ABL1 fusion, rearrangements of PDGFRA, PDGFRB, FGFR1 and/or PCM1-JAK2 fusion), if clinical data are incomplete or if biopsy samples are inadequate." (PMID 34830822, 2021).
chronic myeloid leukemia (15 papers, 2007 to 2026). "Development of more potent TKIs, such as the broad-spectrum ponatinib, active against resistant mutations of FLT3 and BCR-ABL1 in acute and chronic myeloid leukemia, respectively, may be of future clinical benefit in FGFR1 MPN." (PMID 23082258, 2012). "AP24534 (Ponatinib) is a pan BCR–ABL, including BCR–ABLT315I, inhibitor used in the clinic to treat chronic myeloid leukaemia; however, AP24534 exhibits inhibitory activity towards VEGFR-2, FGFR-1 (fibroblast growth factor receptor-1), scr and Lyn (protein tyrosine kinase Lyn) kinases as well." (PMID 25757360, 2015).
dysembryoplastic neuroepithelial tumor (15 papers, 2018 to 2025). A benign glial-neuronal neoplasm. "In addition, successful use of ddPCR for detection of FGFR1 mutations and internal tandem duplication of the tyrosine-kinase domain in dysembryoplastic neuroepithelial tumors has been reported." (PMID 35361262, 2022). "Mutations in CDH1 (A298T) and FGFR1 (K656_T658 > MTP) were identified by targeted sequencing in one patient with a low-grade glioneuronal neoplasm (dysembryoplastic neuroepithelial tumor [DNET]-like) and were conserved at recurrence (Patient #45)." (PMID 33153497, 2020). "Dysembryoplastic neuroepithelial tumors (DNETs) harbored alterations in MAPK/PI3K pathway genes, as was previously reported, including FGFR1 (21%, 4/19), PDGFRA (10%, 2/19), and BRAF (5%, 1/19)." (PMID 37492101, 2023). "Duplication of the FGFR1 TKD has been reported in low-grade astrocytomas (including PA), usually in an extracerebellar location, and in dysembryoplastic neuroepithelial tumor (DNET)." (PMID 29610389, 2018).
astrocytomas (14 papers, 2015 to 2025). "FGFR1 expression is associated with tumor grade in astrocytomas, with high expression found in grade 2 tumors." (PMID 30931252, 2019). "High FGFR1 expression was associated with age, malignancy, tumor location and tumor grade among astrocytomas." (PMID 30931252, 2019). "In astrocytomas, FGFR1 protein expression rises with the WHO grade, and elevated FGFR1 expression in malignant gliomas is generally not attributed to gene amplification, but rather to alterations in the ratio of its splice isoforms." (PMID 41567627, 2025). "Duplication of the tyrosine kinase region of FGFR1 was found in 1/4 pediatric low-grade astrocytomas." (PMID 35432538, 2022). "Based on the ranking results, four genes (RAF1, AKT3, IDH1, and FGFR1) were independent predictors of the survival status of astrocytoma patients." (PMID 31620163, 2019). "We demonstrate migratory phenotypes of low grade pediatric astrocytoma cells in a 2D and 3D environment, varying expression of FGFR1 and its activated form at the protein level and finally distinct responses to FGFR1 inhibition." (PMID 30931252, 2019). "Interestingly, FGFR expression is also correlated to therapeutic resistance and FGFR1 expression is correlated to higher WHO grade in astrocytomas, poor prognosis and invasion." (PMID 40467542, 2025). "Pediatric low grade astrocytoma and ependymoma cell lines showed high percentages of cells expressing VEGFR-1, FGFR-1, EGFR, HGFR and RON (respectively 52–77%, 34–51%, 63–90%, 83–98%, 65–95%, compared to isotype controls)." (PMID 25799134, 2015). "We detected that 18 genes were respectively correlated with overall survival in astrocytoma; moreover, four genes (RAF1, AKT3, IDH1, and FGFR1) were detected as dependent variables for the prediction of the survival status of astrocytoma patients and were capable to predict the survival." (PMID 31620163, 2019). "In our cohort of IDH-mutant diffuse glioma, EGFR Amp was found to co-occur with FGFR1, FGFR2, NTRK3 and RB1 alterations, which was not completely consistent in astrocytoma and oligodendroglioma." (PMID 38595969, 2024).
glioneuronal tumors (14 papers, 2019 to 2025). "Our group and others have described FGFR1 genetic variants linked to the etiology of hereditary and sporadic forms of early-onset, low-grade glioneuronal tumors (LGGNTs)." (PMID 41174249, 2025). "FGFR1 hotspot mutations have also emerged as a molecular hallmark of rosette-forming glioneuronal tumor (RGNT)." (PMID 32085805, 2020). "FGFR1 genetic alterations are associated with brain malignancies, including FGFR1 mutations in familial and sporadic cases of low-grade glioneuronal tumors, suggesting intrinsic mechanisms of selective pressure toward FGFR1 multiple events arising in the context of a quiet genome." (PMID 41174249, 2025). "Among the most important insights gained from landmark sequencing studies examining the molecular landscape of pediatric low grade glial and glioneuronal tumors was the identification of an intragenic duplication of the entire FGFR1 region encoding the tyrosine kinase domain (TKD)." (PMID 32085805, 2020). "Notably, almost all mutations at codon 546 in the FGFR1 gene in glial and glioneuronal tumors have been either p.N546K or p.N546D, and the p.N546S substitution in this DNT is rare but also likely to be activating." (PMID 32859279, 2020). "Among the low grade glial or glioneuronal tumor cohort, all selected cases with BRAF V600E mutation (5/5) or FGFR1 N546K or K656E mutation (5/5) evaluated by HRM-sequencing were also detected with the mdPCR assays." (PMID 33282733, 2020). "To achieve this goal, we evaluated BRAF and FGFR1 mdPCR assays in low grade glial or glioneuronal tumors and H3F3A, IDH1/2 and pTERT mdPCR assays in diffuse gliomas." (PMID 33282733, 2020). "As seen in other glioneuronal tumors, BRAF V600E mutations and FGFR1 alterations (including FGFR1 germline mutations) have been reported in up to 30%–80% of the tumors depending on the composition of the tumor cohort analyzed." (PMID 31181803, 2019). "The histopathological report of the specimen tissue stated a rosette-forming glioneuronal tumor, WHO grade I with a mutation in the fibroblast growth factor receptor 1 (FGFR1) and in the phosphatidylinositol-4,5-bisphosphate 3-kinase catalytic subunit alpha (PIK3CA)." (PMID 39860615, 2025). "FGFR1 alterations may also be shared with other glioneuronal tumors, such as rosette-forming glioneuronal tumor (RGNT) and extraventricular neurocytoma, or with pilocytic astrocytoma (i.e., a circumscribed glioma)." (PMID 38544524, 2024). "Interestingly, these two entities, belonging to two different families (pediatric-type diffuse low-grade gliomas and glioneuronal tumors, respectively), share the same genetic alterations involving the FGFR1 gene." (PMID 38544524, 2024). "The BRAF and FGFR1 mdPCR assays might particularly be useful in the context of pediatric-type glial or glioneuronal tumors." (PMID 33282733, 2020).
Hartsfield syndrome (14 papers, 2014 to 2025). "The FGFR1-related Hartsfield syndrome is a very rare genetic disorder with variably associated congenital defects." (PMID 41562894, 2025). "This study represents a recent recapitulation of the ultrarare clinical entity termed FGFR1-related Hartsfield syndrome, which associates SHFM with craniofacial anomalies and HPE." (PMID 41562894, 2025). "Noteworthy, those symptoms overlap with Hartsfield syndrome caused by FGFR1 loss-of-function mutations." (PMID 25339597, 2015). "Most relevant, mutations in FGFR1 have recently been found in patients with Hartsfield syndrome (OMIM 615465), a congenital condition comprising ectrodactyly." (PMID 24569166, 2014). "However, FGFR1 mutations are often associated with Hartsfield syndrome, which is characterized by holoprosencephaly, ectrodactyly and cleft lip/palate." (PMID 37880672, 2023). "Hartsfield syndrome is a rare genetic condition associated to mutations in the FGFR1 gene." (PMID 28977327, 2017). "The distinctive clinical presentation of the FGFR1-related Hartsfield syndrome is highlighted among genetic disorders with split of the extremities." (PMID 41562894, 2025). "Syndromes associated with cleft palate include those arising from mutations in FGFR1-3; e.g. Apert syndrome (FGFR2), Muenke syndrome (FGFR3), Crouzon syndrome (FGFR2, FGFR3) and Hartsfield syndrome (FGFR1)." (PMID 31613912, 2019). "Additionally, we postulate that the partial overlap between the phenotype of our patient and Hartsfield syndrome (including ectrodactyly, intellectual disability, and genital anomalies) may reflect the common pathogenic mechanism (i.e., disturbed FGFR1 signaling) underlying both conditions." (PMID 25339597, 2015). "Hartsfield-Bixler-Demyer Syndrome, also known as fibroblast growth factor 1 (FGFR1)-related Hartsfield Syndrome, is a rare genetic disorder characterized by a combination of holoprosencephaly and ectrodactyly spectrum disorder, as well as facial anomalies including cleft lip and palate." (PMID 40370525, 2025).